MMP12 (matrix metallopeptidase 12)
Diseases named in the same sentence as MMP12 in open-access papers (continued):
Sharing a sentence is not in itself a finding about the gene and the disease.
experimental autoimmune encephalomyelitis (3 papers, 2019 to 2022). An autoimmune demyelinating disease of the central nervous system that is produced experimentally in animals by the injection of homogenized brain or spinal cord in Freund's adjuvant. "Mmp12 has been reported to be involved in increasing blood–brain barrier permeability and recruitment of macrophages in inflammatory conditions and plays a role in models of experimental autoimmune encephalomyelitis (EAE) by enhancing the anti-inflammatory response." (PMID 34749772, 2021). "In addition, MMP12 has been shown to cleave a wide range of myelin and extracellular matrix molecules in vitro, and the upregulation of MMP12 has been demonstrated in MS, TME, and experimental autoimmune encephalomyelitis." (PMID 30959793, 2019).
gallbladder cancer (3 papers, 2019 to 2021). "MMP12 is significantly upregulated in gallbladder cancer, in which it has been identified as a novel prognostic biomarker." (PMID 32983229, 2020).
head and neck cancer (3 papers, 2016 to 2025). A primary or metastatic malignant neoplasm affecting the head and neck. "Furthermore, a study demonstrated that DRP1 modulates FoxM1 expression, which enhances MMP12 transcription by binding to its promoter region in head and neck cancer (HNC) cells." (PMID 41323781, 2025). "Additionally, IFITM1 has also been shown to enhance migration and invasion in head and neck cancer cells through activation of matrix metalloproteinase 12 (MMP12) and MMP13, key enzymes involved in the degradation of the basement membrane that allows cells to infiltrate into adjacent tissues." (PMID 26897526, 2016).
Hypercholesterolemia (3 papers, 2019 to 2024). An increased concentration of cholesterol in the blood. "Administration of an MMP-12 inhibitor (RXP470.1) protected hypercholesterolemia Apoe−/− mice from Ang II-induced AAA formation and rupture-related death, associated with diminished medial thinning and elastin fragmentation alongside increased collagen deposition." (PMID 38891996, 2024).
intracerebral hemorrhage (3 papers, 2015 to 2022). A cerebrovascular disorder characterized by bleeding into one or both cerebral hemispheres including the basal ganglia and the cerebral cortex. "The Hes5 was reported to be downregulated after brain injury, while the Mmp12 expression was significantly increased in intracerebral hemorrhage." (PMID 35501920, 2022). "MMP-12 expression is upregulated after intracerebral hemorrhage, which accounts for approximately 15–20% of all strokes." (PMID 25955565, 2015). "Suppression of MMP-12 with non-specific inhibitors or genetic deletion of MMP-12 led to enhanced recovery after SCI and intracerebral hemorrhage (ICH)." (PMID 36267234, 2022).
Lung Injury (3 papers, 2013 to 2025). "Disruption of Mmp12 gene resulted in reduced total BAL protein, reduced neutrophil infiltration into the lung airspaces and reduced lung injury following an immune complex-induced acute lung injury." (PMID 40496925, 2025).
periodontal disease (3 papers, 2021 to 2023). "Nevertheless, further research is needed to disclose the underlying molecular mechanism of MMP12 in periodontal disease." (PMID 36902078, 2023). "Despite the fact that periodontal disease is characterized by bone degradation, the effect of MMP12 on alveolar bone loss is poorly understood." (PMID 36902078, 2023). "MMP12 has been linked to pathological connective and osseous tissue metabolisms in periodontal disease patients." (PMID 36902078, 2023). "Recent reports show MMP12 has been implicated in the pathogenesis of periodontal diseases." (PMID 36902078, 2023). "This indicates that MMP12 may be a risk factor for periodontal disease." (PMID 36902078, 2023). "Researchers are allowed to use advanced diagnostic technology to investigate precise chair-side tests or mouth-rinse MMP12 screening tests for monitoring periodontal diseases and other oral disorders." (PMID 36902078, 2023). "Better periodontal status has been correlated with decreased expression of MMP12 in the GCF of patients with juvenile aggressive periodontal disease." (PMID 36902078, 2023). "As a result, a functional clinical study strategy is preferable for elucidating MMP12’s precise role in periodontal diseases." (PMID 36902078, 2023). "The study concluded that MMP-12 reflects various aspect of periodontal disease and the levels are contrarily affected by the presence of tumor." (PMID 33892690, 2021). "Highly expressed in the tissue of periodontal diseases, TMD, and OSCC, MMP12 may be regarded as the diagnostic marker of these common oral disorders." (PMID 36902078, 2023). "In addition, strategies to inhibit the expression of MMP12 and other MMPs have been used in the treatment of periodontal diseases." (PMID 36902078, 2023). "However, MMP12 expression, on the other hand, was found to follow a distinct pattern in other periodontal diseases." (PMID 36902078, 2023). "None of these MMP12 inhibitors is yet tested for their efficacy in oral diseases, such as periodontal diseases, TMD, and OSCC." (PMID 36902078, 2023). "Thus, the increased expression of MMP12 in the GCF, saliva, and gingival tissues of periodontal disease patients suggests that this enzyme may be helpful as a diagnostic marker of disease status and a predictor of future disease." (PMID 36902078, 2023).
Sepsis (3 papers, 2014 to 2022). Sepsis is defined as life-threatening organ dysfunction caused by a dysregulated host response to infection. "Macrophage-specific MMP12 both initiates and terminates neutrophil recruitment by chemokine cleavage, and MMP12 deficiency results in increased mortality in sepsis." (PMID 28179412, 2017). "The association of the MMP-1 (-1607 1G/2G) SNP and sepsis might be due to linkage disequilibrium with the MMP-13 SNP because the MMP-13 and MMP-1 genes are both located in the same cluster of the chromosome 11q22-23 along with the MMP-3, MMP-7, MMP-8, MMP-10, MMP-12, and MMP-20 genes." (PMID 24833564, 2014).
Trichiasis (3 papers, 2012 to 2018). Inversion and rubbing of the eyelashes against the globe of the eye. "This identified a variety of pro-inflammatory (IL1B, TNFA, S100A7, CXCL5, NOS2A) and tissue remodelling factors (MMP7, MMP9 and MMP12), which were associated with conjunctival scarring and trichiasis before surgery." (PMID 23285311, 2012). "MMP7 has consistently been found to be upregulated in scarring trachoma and trichiasis alongside MMP9 and MMP12 but there is less evidence for a role of MMP7 in active trachoma." (PMID 28966918, 2017).
ulcerative colitis (3 papers, 2021 to 2024). An inflammatory bowel disease involving the mucosal surface of the large intestine and rectum. "Interestingly, APOE, C1QB, and matrix metalloproteinase 12 (MMP12) are highly expressed in C1QB+ macrophages, IL-1B+ macrophages and CALD1+ macrophages from ulcerative colitis patients." (PMID 39095853, 2024).
age (2 papers, 2020 to 2025). A temporal measurement of the time period elapsed since an identifiable point in the life cycle of an organism. "In this model, deficiency in αvβ6 integrins leads to the formation of age-related emphysematous changes by the enhanced expression of macrophage metalloelastase (MMP12)." (PMID 40649983, 2025).
angina pectoris (2 papers, 2019 to 2020). The symptom of paroxysmal pain consequent to MYOCARDIAL ISCHEMIA usually of distinctive character, location and radiation. "Notably, patients with STEMI compared to patients with stable angina pectoris had stronger elevated plasma levels of MMP12 due to an imbalance between MMP12 and TIMP1." (PMID 31450823, 2019). "The stronger elevated plasma levels of MMP12 and imbalance between MMP12 and TIMP1 was observed in patients with STEMI compared to patients with stable angina pectoris." (PMID 32486345, 2020).
Ascending aortic dissection (2 papers, 2022 to 2024). A separation of the layers within the wall of the ascending aorta. "However, caution should be taken when considering MMP-12 inhibition for the treatment of individuals harboring non-atherosclerotic dilatations, such as patients with bicuspid aortic valves and deemed at risk of ascending aortic dissection." (PMID 38891996, 2024).
Autoimmunity (2 papers, 2018 to 2021). The occurrence of an immune reaction against the organism's own cells or tissues. "We have utilized Mmp12-/- mice to demonstrate the pivotal role of this metalloproteinase in driving the autoimmunity in the CS+Eln model." (PMID 33828547, 2021). "Although this clinical association does not prove a mechanistic link for MMP12 in protection from autoimmunity in human disease, it supports the findings from our animal model studies." (PMID 29925830, 2018).
Barrett esophagus (2 papers, 2018 to 2025). Esophageal lesion lined with columnar metaplastic epithelium which is flat or villiform. "High expression of AZIN1-AS1, COX6C, MMP12 and PVT1 might be associated with a worse survival outcome both in TCGA ESCC and esophageal adenocarcinoma (EAC) datasets." (PMID 40569942, 2025). "Research focused on Barrett’s esophagus and esophageal adenocarcinoma have also suggested that BIRC2, BIRC3, MMP12, MYC, PVT1, and YAP1 may be ecDNA-related oncogenes." (PMID 40569942, 2025). "Although our study did not reveal correlation between MMP3–1612 6A/5A, MMP12 -82A/G polymorphisms and RHD in Han population, studies have shown a combined effect of MMP1–1607 1G/2G, MMP3–1612 6A/5A and MMP12-82A/G polymorphisms associated with esophageal adenocarcinoma (EA) risk in Caucasian." (PMID 29458338, 2018).
bronchitis (2 papers, 2020 to 2021). An acute or chronic inflammatory process affecting the bronchi. "We demonstrate that autophagy promoted the bronchitis-like airway inflammation, likely through facilitation of both early MMP12 induction in macrophages and late airway epithelial injury." (PMID 33828547, 2021). "In conclusion, our findings demonstrate that autophagy promoted the bronchitis-like airway inflammation, likely through facilitation of both early MMP12 induction in macrophages and late airway epithelial injury." (PMID 33828547, 2021).
chronic rhinosinusitis (2 papers, 2021 to 2024). Chronic form of sinusitis. "The present study aimed to investigate the role of MMP-12 in inducing epithelial-mesenchymal transition (EMT) in chronic rhinosinusitis with nasal polyps (CRSwNP)." (PMID 39739687, 2024).
Cirrhosis (2 papers, 2020 to 2023). A chronic disorder of the liver in which liver tissue becomes scarred and is partially replaced by regenerative nodules and fibrotic tissue resulting in loss of liver function. "Similarly, serum MMP12 level also exhibited significant increases in patients with cirrhosis and F4 fibrotic stage (P < 0.001)." (PMID 31903104, 2020). "QuantSeq 3′ mRNA sequencing revealed thirty-three downregulated genes associated with ECM after the NK cell treatment of CCl4-induced cirrhosis, including six MMP genes (MMP3, MMP8, MMP9, MMP11, MMP12, and MMP14)." (PMID 37189708, 2023). "Importantly, we found an inhibitory loop between MMP12 and pro-inflammatory cytokines and discovered an MMP12 rescue effect of TSG-6, which may partly explain the aggravating process of cirrhosis and antifibrotic mechanisms of TSG-6 and MSCs." (PMID 31903104, 2020). "Additionally, we found a feedback loop between TSG-6, MMP12 and pro-inflammatory cytokines (TNF-α, IL-6, and IL-1β), which may improve our understanding of the aggravating process of cirrhosis and antifibrotic mechanisms of TSG-6 and MSCs." (PMID 31903104, 2020).
contact dermatitis (2 papers, 2020 to 2021). An inflammatory skin condition caused by direct contact between the skin and either an irritating substance or an allergen. "It was also reported that M2 macrophages secrete MMP12, which is an elastase, and are involved in the pathological conditions of contact dermatitis." (PMID 33121169, 2020).
coronary artery atherosclerosis (2 papers, 2011 to 2021). "The MMP12 −82A>G polymorphism has been associated with coronary atherosclerosis." (PMID 21887284, 2011). "In our study, MMP-7 and MMP-12 levels were also significantly higher in patients with CHD and verified coronary artery atherosclerosis than in the control group." (PMID 34205079, 2021).
endometrial cancer (2 papers, 2020 to 2022). Primary or metastatic malignant neoplasm involving the endometrium (mucous membrane that lines the endometrial cavity). "The results of our study indicate that TA ameliorated the endometrial cancer induced by MNU and estradiol by regulating the macrophage/MMP-12/plasminogen/angiostatin signal transmission pathway." (PMID 35371322, 2022). "Particularly, expression of TFAP2A, MMP12, TOP2A, ASPM and CFB were higher in endometrial cancer relative to normal tissues." (PMID 32555395, 2020).
glomerular disease (2 papers, 2014 to 2016). "Given that similar trends were observed for MCP-1 and CD11b mRNA levels and MCP-1 protein levels, these results indicate that the loss of MMP-12 function inhibits renal inflammation in glomerular disease progression resulting from HFD." (PMID 26822129, 2016). "Given the broad substrate specificity of MMP-12, we investigated whether MMP-12 modulates glomerular disease progression induced by HFD." (PMID 26822129, 2016). "Since we have previously documented a role for biomechanical strain in the induction of MMPs and the acceleration of glomerular disease in Alport mice we assessed the effect of FAK inhibition by TAE226 on biomechanical stretch-mediated induction of MMP-10 and MMP-12." (PMID 24915008, 2014).
glomerulonephritis (2 papers, 2015 to 2025). A renal disorder characterized by damage in the glomeruli. "A published study researched the mechanism of kidney fibrosis, exploring the expression and localization of MMP-12 and associated regulatory molecules in the kidneys of experimentally induced glomerulonephritis in mice." (PMID 39996798, 2025). "Real-time PCR analysis of whole kidneys identified a marked increase in the gene expression of leukocyte markers (CD68, CD3e), proinflammatory cytokines (TNF-α, IFN-γ, CCL2) and macrophage elastase (MMP-12) in untreated and vehicle-treated mice at day 15 of glomerulonephritis." (PMID 26700873, 2015).
head and neck squamous cell carcinoma (2 papers, 2014 to 2023). A squamous cell carcinoma that arises from any of the following anatomic sites: lip and oral cavity, nasal cavity, paranasal sinuses, pharynx, larynx, and salivary glands. "MMP7, MMP9, MMP11, MMP12 and MMP13 were all up-regulated in head and neck squamous cell carcinoma." (PMID 36941602, 2023).
infective endocarditis (2 papers, 2012 to 2013). Infective endocarditis (IE) is an infection of the inner lining of the heart chambers (endocardium) and valves. "MMP-12 expression in cardiac valves taken from patients suffering from infective endocarditis has been shown to be elevated and human and animal studies have established the presence and activity of MMP-9 on cardiac-related remodeling." (PMID 23805173, 2013).
influenza (2 papers, 2008 to 2019). An acute viral infection of the respiratory tract, occurring in isolated cases, in epidemics, or in pandemics; it is caused by serologically different strains of viruses (influenzaviruses) designated A, B, and C, has a 3-day incubation period, and usually lasts for 3 to 10 days. "MMP-12 mRNA levels were increased in all mice, especially smoke and influenza mice, at d3 only." (PMID 18627612, 2008).
interstitial lung disease (2 papers, 2020 to 2025). A diverse group of lung diseases that affect the lung parenchyma. "THBS4 has been associated with interstitial lung disease, a group of conditions in which MMP-12 is often increased and plays a pro-fibrotic role." (PMID 39794761, 2025).
intestinal tumor (2 papers, 2024 to 2025). "When expressed in macrophages, MMP12 may inhibit intestinal tumor growth by influencing macrophage polarization." (PMID 39764138, 2024).
kidney damage (2 papers, 2024). "In particular, Mmp7, Mmp10, and Mmp12 were highlighted for their differential expression between strains and their potential role in influencing the severity of kidney damage." (PMID 38674390, 2024).
Lewis lung carcinoma (2 papers, 2014). "An increase in Lewis lung carcinoma (LLC) pulmonary metastasis was shown in MMP12-deficient mice, while regular MMP12 expression was associated with reduced tumour-associated microvessel density in vivo." (PMID 26316944, 2014).
lung squamous cell carcinoma (2 papers, 2023 to 2025). "MMP12 encodes a matrix metalloproteinase and serves as an immune cell-related biomarker for squamous cell carcinoma of the lung, reflecting disease status and prognosis." (PMID 40092988, 2025).
lymph node metastasis (2 papers, 2013 to 2024). "We compared the MMP-12 mRNA levels between cancer tissues and matched surrounding normal tissues, between TNM stage I and stage II/III, as well as between tumors with lymph node metastasis and without, in cases of NSCLC." (PMID 24137407, 2013).
Lymphadenopathy (2 papers, 2018 to 2020). Enlargement (swelling) of a lymph node. "Similarly, loss-of-MMP12 increases IFN-γ–dependent proinflammatory markers and iNOS+/MHC class II+ macrophage accumulation with worse lymphadenopathy, arthritic synovitis and lupus glomerulonephritis." (PMID 29925830, 2018).
meningitis (2 papers, 2013 to 2019). A disorder characterized by acute inflammation of the meninges of the brain and/or spinal cord. "Encephalitis and meningitis patients differed with respect to other chemokines (CXCL11) and MMPs (MMP-3, MMP-8, MMP-9, and MMP-12), indicating that different location of the virus gives rise to qualitative differences in the ensuing inflammatory response." (PMID 30777092, 2019).
metastatic cancer (2 papers, 2011 to 2017). A carcinoma which has spread from the original site of growth to another anatomic site. "These included genes which are implicated in inflammation and inflammatory responses to cancer (PTX3, IL8, TNFSF10, SERPINB13 and ANKRD1) and those involved in cell adhesion, cell migration and ECM degradation of importance in metastatic cancer (MMP12, MMP1 and ADAM19)." (PMID 28555042, 2017). "Furthermore, it was found that Runx2 is ectopically expressed in metastatic cancer cells but not in non-metastatic cancer cells, and that several genes required for bone development and turnover, such as opn, bsp, mmp12 etc., are activated by Runx2." (PMID 21649908, 2011).
multiple sclerosis (2 papers, 2015 to 2018). A progressive autoimmune disorder affecting the central nervous system resulting in demyelination. "MMP-12 expression is highly upregulated in neurons and glial cells following peripheral nerve injury, brain ischemic stroke, spinal cord injury, epilepsy and multiple sclerosis." (PMID 30044455, 2018). "In the case of the central nervous system (CNS), MMP-12 might be responsible for blood–brain barrier (BBB) disruption occurring in several neurological diseases/disorders characterized by inflammatory processes, such as spinal cord injury, multiple sclerosis, and ischemic or hemorrhagic strokes." (PMID 30044455, 2018).
nasal polyps (2 papers, 2021 to 2024). "Furthermore, MMP-12 was shown to promote tissue proliferation in vitro, suggesting that it may contribute to the development of nasal polyps in CRS." (PMID 39739687, 2024). "In a study of nasal polyps, a common complication of CRS, MMP-12 was found to be upregulated in the polyp tissues compared to healthy nasal mucosa." (PMID 39739687, 2024). "The mRNA expression of CD206 and CD163, known as markers of M2 macrophages, as well as the expression of mRNA MMP12, were examined in normal uncinate process (UP), CRS without nasal polyp (CRSsNP) UP, CRS with nasal polyp (CRSwNP) UP, and CRSwNP NP tissues." (PMID 39739687, 2024).